LHX4 (LIM homeobox 4)
Description:
May play a critical role in the development of respiratory control mechanisms and in the normal growth and maturation of the lung. Binds preferentially to methylated DNA.
Synonyms: Gsh4; CPHD4
Tractability: No criterion of Open Targets' tractability assessment is met for any kind of drug.
Gene: Protein-coding gene on chromosome 1 (180,230,188 to 180,278,984, forward strand). Ensembl gene ENSG00000121454.
Subcellular location: Nucleus
Subcellular location (Human Protein Atlas): Nuclear speckles
Pathways (Reactome):
Developmental Biology: Regulation of expression of SLITs and ROBOs
Gene Ontology:
Molecular function: DNA-binding transcription activator activity, RNA polymerase II-specific; methyl-CpG binding; protein binding; sequence-specific DNA binding; sequence-specific double-stranded DNA binding; DNA-binding transcription factor activity, RNA polymerase II-specific; RNA polymerase II transcription regulatory region sequence-specific DNA binding; DNA binding; zinc ion binding
Biological process: positive regulation of transcription by RNA polymerase II; neuron differentiation; regulation of transcription by RNA polymerase II; regulation of DNA-templated transcription
Cellular component: chromatin; nucleus
Genetic constraint (gnomAD): Loss-of-function variants: 16 observed, 41.29 expected, observed/expected ratio (o/e) 0.39, 90% interval 0.26 to 0.59. The upper end of that interval is the gene's LOEUF score, 0.59, which puts it in group 2 of 6, group 1 being the genes least tolerant of losing a copy. Missense variants: 439 observed, 538.9 expected, observed/expected ratio (o/e) 0.81, 90% interval 0.75 to 0.88. Synonymous variants: 206 observed, 210.43 expected, observed/expected ratio (o/e) 0.98, 90% interval 0.87 to 1.1.
Homologues: Orthologues: chimpanzee LHX4 (100% identical), dog LHX4 (99% identical), mouse Lhx4 (99% identical), guinea pig LHX4 (99% identical), pig LHX4 (98% identical), rat Lhx4 (98% identical), rabbit LHX4 (95% identical), macaque LHX4 (94% identical), zebrafish lhx4 (83% identical), tropical clawed frog qsox1 (78% identical). Paralogues in human: LHX3 (64% identical), LHX1 (37% identical), LHX5 (36% identical), LMX1B (30% identical), LMX1A (30% identical), ZFHX4 (29% identical), ZFHX3 (27% identical), LHX8 (23% identical), LHX9 (23% identical), LHX2 (23% identical), LHX6 (22% identical), ZFHX2 (21% identical), and 8 more.
Diseases named in the same sentence as LHX4 in open-access papers:
LHX4 is named in the same sentence as 43 diseases in open-access papers, as found by Europe PMC text mining. Sharing a sentence is not in itself a finding about the gene and the disease. The quoted sentences say what the papers report.
pituitary hormone deficiency (13 papers, 2012 to 2025). "The homozygous status of the variant p.T126M in LHX4 has been reported in a congenital lethal form of hypopituitarism in three relatives who died within the first week of life." (PMID 40150646, 2025). "Human patients heterozygous for a mutation in LHX4 protein suffer from combined pituitary hormone deficiency (CPHD), short statures, reproductive and metabolic disorders and abnormalities of the sella turcica." (PMID 39000439, 2024). "Patients with LHX4 mutation suffer from combined pituitary hormone deficiency (CPHD), short statures, reproductive and metabolic disorders and lethality in some cases." (PMID 39000439, 2024). "LHX4 mutations can cause isolated growth hormone deficiency or combined pituitary hormone deficiency (CPHD)." (PMID 34948037, 2021). "To date, 8 heterozygous LHX4 mutations have been reported as responsible of combined pituitary hormone deficiency (CPHD) in Humans." (PMID 25955177, 2015). "In girls with TS, the transcription factor LHX4, which when mutated is associated with multiple pituitary hormone deficiencies, was associated with growth response." (PMID 23761422, 2013). "However, through lhx4 knockdown by 4MO, we found that the phenotypes of zebrafish embryos were similar to human combined pituitary hormone deficiency (CPHD), characterized by a deficiency of the growth hormone and retardation." (PMID 33479361, 2021). "Another region was also identified including LHX4, which was found to be altered in a case report of a patient with combined pituitary hormone deficiency and CM1 (p.P366T LHX4)." (PMID 39458107, 2024). "In the pituitary, mutations in Lhx3 and Lhx4 are also the causes for combined pituitary hormone deficiency (CPHD), indicating that Ldb1/Lhx3/Lhx4 complex is indispensable for pituitary development." (PMID 30127719, 2018). "HESX1, GLI2, and SOX3 mutations have been linked to hypopituitarism, and mutations in SOX2, LHX3, LHX4, and PROP1 may cause gonadotropin deficiency." (PMID 34948037, 2021). "In conclusion, extra-pituitary findings may provide clues for the diagnosis of particular gene mutations including GLI2, HESX1, LHX4, SOX3, and OTX2 which are involved in the development and differentiation of the pituitary gland resulting in a variety of pituitary hormone deficiencies." (PMID 31782289, 2020).
acute lymphoblastic leukemia (3 papers, 2008 to 2017). Leukemia with an acute onset, characterized by the presence of lymphoblasts in the bone marrow and the peripheral blood. "Recently, using quantitative real-time reverse-transcription PCR, it was found that the LHX4 mRNA is expressed at high levels in leukemic cells and in an acute lymphoblastic leukemia (ALL) cell line." (PMID 18179710, 2008).
breast carcinoma (2 papers, 2017 to 2019). "E2­activated HSF1 was transcriptionally potent and several genes essential for breast cancer cells growth and/or ERα action, including HSPB8, LHX4, PRKCE, WWC1, and GREB1, were activated by E2 in a HSF1-dependent manner." (PMID 31614463, 2019).
Anosmia (1 paper, 2021). An inability to perceive odors. "P/LP variants were detected in patients presenting with anosmia/hyposmia in genes previously reported for nIHH (GNRHR) or SOD/CPHD (LHX4, SOX3)." (PMID 34198905, 2021).
Chiari malformation (1 paper, 2024). A rare genetic brain malformation characterized by displacement of the brain stem and cerebellum through the foramen magnum. "Cerebral malformations such as hypoplastic corpus callosum or Chiari malformation suggest LHX4 gene variants." (PMID 39415786, 2024).
cleft palate (1 paper, 2020). Cleft palate is a fissure type embryopathy that affects the soft and hard palate to varying degrees. "In hESCs, TCDD-treatment resulted in significant upregulation of LHX4 and SIX3, which are associated with cleft palate, the hallmark phenotype of TCDD toxicity." (PMID 33260776, 2020).
colorectal cancer (1 paper, 2019). A primary or metastatic malignant neoplasm that affects the colon or rectum. "As for other LHX members, early studies revealed that LHX2 promoted tumor cell proliferation in pancreatic ductal adenocarcinoma, and LHX4 facilitated the development of colorectal cancer, both via enhancing Wnt/TCF4/β-catenin pathway." (PMID 31788020, 2019).
congenital stationary night blindness (1 paper, 2020). "Retina-specific deletion of Lhx4 in mice results in a visual defect resembling human congenital stationary night blindness." (PMID 32937137, 2020).
female infertility (1 paper, 2024). Diminished or absent ability of a female to achieve conception. "Thus, we conclude that gonadotropin deficiency, or the combination of gonadotropin and Tshb deficiencies, is the source for the female infertility of homozygous lhx4-mutant females." (PMID 39000439, 2024). "In accordance with the observed female infertility, the RFP intensity in the lhb-expressing gonadotrophs of the homozygous lhx4-mutant females was nearly undetectable." (PMID 39000439, 2024).
heart failure (1 paper, 2019). Inability of the heart to pump blood at an adequate rate to meet tissue metabolic requirements. "Heart failure constitutes a vital risk in newborns with the LHX4 mutation-related multiple hormone deficiency." (PMID 29739730, 2019).
Kallmann syndrome (1 paper, 2021). Kallmann syndrome (KS) is a developmental genetic disorder characterized by the association of congenital hypogonadotropic hypogonadism (CHH) due to gonadotropin-releasing hormone (GnRH) deficiency, and anosmia or hyposmia (with hypoplasia or aplasia of the olfactory bulbs). "Perhaps a specific sort of defect in GNRHR, LHX4, or SOX3 can result in a complete clinical picture of Kallmann syndrome with smell disturbances." (PMID 34198905, 2021).
lymphoma (1 paper, 2008). A malignant (clonal) proliferation of B- lymphocytes or T- lymphocytes which involves the lymph nodes, bone marrow and/or extranodal sites. "There is no published information regarding the role of LHX4 in lymphoma thus further analysis is required to determine the significance of increased expression of LHX4 in HL and ALCL." (PMID 18179710, 2008).
malnutrition (1 paper, 2024). Inadequate nutrition resulting from poor diet, malabsorption, or abnormal nutrient distribution. "Thus, the poor mobilization of the lhx4 mutants may have led to a failure in the competition over food when raised with their WT siblings, which may account for their malnutrition and reduced body size, a possibility that warrants further inquiry." (PMID 39000439, 2024). "The reproductive impairments of the homozygous lhx4-mutant females could also be explained by malnutrition and a reduced body size, although our findings of lower fshb mRNA levels and depleted lhb-expressing gonadotrophs in adult homozygous lhx4 mutants would be a more reasonable explanation." (PMID 39000439, 2024).
pituitary deficiency (1 paper, 2019). "We identified CBX2 regulated genes associated with polycystic ovary syndrome (PCOS) such as TGFβ, MAP3K15 and DKK1, as well as genes implicated in premature ovarian failure (POF) (i.e. POF1B, BMP15 and HOXA13) and the pituitary deficiency (i.e. LHX4 and KISS1)." (PMID 31745224, 2019).
tumor (5 papers, 2009 to 2025). "Among them, MZF1, OGT, LHX4, and MED12 have been implicated in tumor stemness, drug resistance, and immune escape mechanisms." (PMID 40963600, 2025). "Lhx3 and Lhx4 regulate proliferation and differentiation of pituitary-specific cell lineages and are expressed in subsets of lymphocytes and thymocyte tumor cell lines." (PMID 19997623, 2009).
cancer (1 paper, 2012). A tumor composed of atypical neoplastic, often pleomorphic cells that invade other tissues. "A third molecule that was significantly less expressed in PC3 cells with simvastatin treatment was Lhx4, a molecule abundantly expressed in many cancers, but exact function is yet to be determined." (PMID 22974127, 2012).
LHX4 also shares sentences with these, for which no sentence is quoted: congenital hypopituitarism (3 papers); pituitary stalk interruption syndrome (2); bacterial infection (1); bone disorder (1); cervical cancer (1); chronic myeloid leukemia (1); Chudley-McCullough syndrome (1); clear cell renal cell carcinoma (1); cone-rod dystrophy (1); congenital hypogonadotropic hypogonadism (1); follicular lymphoma (1); genetic disorder (1); Gonadotropin deficiency (1); head and neck squamous cell carcinoma (1); holoprosencephaly (1); hypogonadotropic hypogonadism (1); infection (1); metabolic disorders (1); myopathy (1); Nephroblastoma (1); ovarian carcinoma (1); pancreatic ductal adenocarcinoma (1); Pituitary Hormone Deficiency, Combined, 4 (1); polycystic ovary syndrome (1); premature ovarian failure (1); prostate carcinoma (1); X-linked recessive hypophosphatemic rickets (1).